TNF (tumor necrosis factor)
Diseases named in the same sentence as TNF in open-access papers (continued):
Sharing a sentence is not in itself a finding about the gene and the disease.
epilepsy (continued). "Finally, the expression of four key genes (IER3, TNF, GPANK1, and ATF6B) in the hippocampus of epilepsy mouse model was quantified using PCR." (PMID 41466027, 2026). "Our findings add to the body of evidence suggesting that targeting immune pathways, particularly those involving TNF and IER3, may offer therapeutic benefits in epilepsy management." (PMID 41466027, 2026). "We found that TNF-α, sIL-2R, gross motor DQ, and adaptive DQ were greater in children with CP without epilepsy (EP) than in those with EP." (PMID 40124353, 2025). "Inflammatory mediators, such as cyclooxygenase-2 and nuclear factor κB (NF-κB), along with inflammatory factors like interleukin-1β, IL-6, tumor necrosis factor (TNF) -α, and prostaglandin E2 (PGE2), play a significant role in the occurrence and progression of epilepsy." (PMID 39121110, 2024). "Elevated concentrations of interleukin-6 (IL-6), interferon-gamma (IFN-γ), and interleukin-17A (IL-17A) have been observed in the plasma during the interictal phase of epilepsy, whereas IL-1β, TNF-α, and IL-10 did not rise in comparison to a healthy group." (PMID 39861097, 2024). "Omrani and colleagues found that EPA and DHA supplementation in patients with refractory epilepsy experienced decreased seizures as well as TNF-alpha and IL-6 concentrations, suggesting a mechanistic commonality between ASD and epilepsy that can be targeted using PUFA supplementation." (PMID 38398876, 2024). "Therefore, we further investigated the levels of serum biomarkers, including SIRT3, IL-6, IL-1β, TNF-α, and CRP in epilepsy patients." (PMID 39091611, 2024). "Proinflammatory factors, such as IL‐1β, IL‐6, TNF‐α, and TGF‐β, were reported to play important roles in epileptogenesis, indicating that inflammatory response in the brain is a crucial mechanism in the pathophysiology of epilepsy." (PMID 38357846, 2024). "Alterations in miRNA expressions may be involved in the pathogenesis of epilepsy by regulating the expressions of inflammatory factors, such as IL-1, INF-α, and tumor necrosis factor alpha (TNF-α)." (PMID 39268188, 2024). "Evidence from preclinical studies shows that animal models exposed to lipopolysaccharide (LPS)-induced inflammatory response develop seizure due to pronounced levels of pro-inflammatory cytokines, such as IL-1β, TNF-α, and HMGB1, as seen in epilepsy comorbidities." (PMID 37239204, 2023). "Alteration in miRNA expression may be involved in epilepsy pathogenesis by regulating the expression of inflammatory factors, such as IL-1, INF-α and TNF-α." (PMID 35328484, 2022). "Furthermore, these authors also studied seven adult patients with epilepsy treated with VNS in whom a reduction of IL-6, IL-1β, and TNF blood production was observed." (PMID 36010024, 2022). "In addition, alterations in circulatory levels of proinflammatory cytokines such as interleukin-1β, tumor necrosis factor-α (TNF-α), IL-6, and interferon-γ have been reported in an animal model of epilepsy following DBS33." (PMID 34215817, 2021). "TNF-α increases the number of Glu receptors and induces the ingestion of GABA, which in turn reduces the inhibitory drive and induces neuronal excitation, which leads to the development of epilepsy." (PMID 33746751, 2021). "To conclude, dysregulated miRNA expression may be involved in epilepsy pathogenesis by regulating the expression of inflammatory factors (e.g., IL-1, INF-α, and TNF-α)." (PMID 33776649, 2021). "Studies have noted increased TNF-α serum levels in individuals with epilepsy compared with normal subjects." (PMID 33959658, 2021). "This may be attributed to the reciprocal effects of epilepsy and PSD on these cytokines as clear from the decrease obtained in TNF-α during the chronic phase of the pilocarpine model and the increase in TNF-α, IL-6, and IL-1β in PSD animals." (PMID 33643575, 2021). "Meta-analysis reveals many studies of elevated TNF-α level in patients with epilepsy in serum and cerebrospinal fluid (CSF), however not in all reports." (PMID 32403392, 2020).
epilepsy (continued). "The anti-TNF-α therapy for epilepsy was considered although was not applied due to the suspected risks of infection and cancer development." (PMID 32190059, 2020). "To elucidate the mechanism of SE-induced vasogenic edema, we investigated the roles of tumor necrosis factor (TNF)-α in blood-brain barrier (BBB) disruption during vasogenic edema and its related events in rat epilepsy models provoked by pilocarpine-induced SE." (PMID 22240205, 2012). "Notably, the role of TNF-α signaling in epilepsy that develops after TBI has not yet been identified." (PMID 36997619, 2023). "In addition, TNF-α can control the glutamate receptor transport via TNF receptor 1 and the TNF receptor 2, and these receptors promote neuron firing by increasing glutamate levels in the synaptic cleft; therefore, TNF-α plays a role in epilepsy." (PMID 36212646, 2022). "TNF-α expression in the perifocal zone, both in the cortex and in the white matter of the temporal lobe, exceeded its expression in biopsies of people without epilepsy." (PMID 36293411, 2022). "Moreover, we corroborated our findings in resected brain tissue from patients with epilepsy who had no known peripheral inflammatory disease, suggesting that TNFα-mediated neuroinflammation contributes to neuronal hyperexcitability of diverse etiology." (PMID 34511110, 2021). "Unlike IL-1β, tumor necrosis factor-α exerts dual effects on epilepsy." (PMID 33597846, 2020). "Besides, FK506 also significantly reduced the levels of factors involved in inflammatory response such as vascular cell adhesion molecule-1 (VCAM-1), intercellular adhesion molecule-1 (ICAM-1), tumor necrosis factor-α (TNF-α), and Protein Kinase C δ (PKCδ) that rise after epilepsy." (PMID 31572289, 2019). "These suggest that certain drugs used to treat epilepsy could be employed as adjuvants in SCI treatment; however, these observations and suggestions were not directly linked to TNF by the original researchers, and the mechanisms proposed are unclear." (PMID 30700814, 2019). "Further, the role of TNFα signaling in epilepsy that develops after TBI has not yet been explored." (PMID 31717556, 2019). "Studies based on an epilepsy mouse model reproducing chronic human mesial temporal lobe epilepsy with sclerotic hippocampus (MTLE-HS), demonstrated that impairment of astrocyte gap junction coupling starts early (within 4 h after SE), and was induced by the presence of IL-1β, TNF and LPS." (PMID 29928494, 2018). "TNF-α showed no brain region-specific or epilepsy-related differences." (PMID 27737716, 2016). "In fact, IL-6, IL-1β, and MIP-1α levels were higher in the temporal cortex than in the hippocampus, and TNF-α showed no regional or epilepsy-related differences, though levels in entorhinal cortex may have been lower than either the hippocampus or temporal cortex." (PMID 27737716, 2016). "Regardless of the role of the inflammatory system in epilepsy, it will be important to pursue the anticonvulsant and antiepileptogenic effects of the antagonists of shared mediators of inflammation and synaptic plasticity, including cyclooxygenase products, IL-1β, IL-6, and TNFα." (PMID 26464976, 2015). "Although epilepsy is not considered a primary immune-mediated disease, DRE microglial clusters 7, 5, 9 and 11 were characterized by high gene expression levels of TNF, HLA-DRA and HLA-DPB1 and low CX3CR1 and P2RY12 gene expression levels." (PMID 35739273, 2022). "Previously, we showed that IL-1β, TNF-α, and other proinflammatory mediators are overexpressed in VPA-resistant epilepsy, but we did not explore the mechanisms that trigger this phenomenon." (PMID 34497517, 2021). "Finally, although we validated the altered expression of IER3, TNF, GPANK1, and ATF6B in multiple epilepsy models, we did not investigate the correlation between their expression levels and behavioral seizure outcomes (e.g., Racine scores, seizure frequency)." (PMID 41466027, 2026).
epilepsy (continued). "Interestingly, seizures lead to expression of TNF-α in the hippocampus and increase seizure sensitivity through activation of TNFR1, while activation of TNFR2 plays an antiepileptic role in vivo, Lack of TNFR2 or both led to increased epilepsy sensitivity in mice." (PMID 38074156, 2023).
mastitis (218 papers, 2009 to 2026). Inflammation of breast tissue during lactation or postpartum due to an obstructed duct or infection. "In the mouse mastitis model, mastitis was associated with upregulated IL‐6, TNFα, and IL‐1β levels in the bloodstream, immune cell aggregation in the colon, disintegration of TJ, and poorly aligned intestinal villi." (PMID 40552401, 2025). "The interaction between mint components and core targets shows that ursolic acid in mint is associated with TNF, IL–6, and IL–1β, reflecting its potential active role in the treatment of mastitis in dairy cows." (PMID 40005889, 2025). "Studies have shown that mastitis pathogenesis involves LPS and pathogenic microorganisms stimulating the release of pro-inflammatory cytokines such as IL-1β and TNF-α, leading to inflammatory damage in mammary tissues and marked increases in SCC." (PMID 40901059, 2025). "Mouse mastitis from S. simulans and S. aureus superinfection was associated with a decrease in GM-CSF but an increase of TNF-α and the anti-inflammatory IL-10." (PMID 40757863, 2025). "Previous studies have shown that TNF-α, IL-1β, and IL-6 are closely related to mastitis pathogenesis, and expression of these three inflammatory cytokines are significantly increased in mastitis caused by S. aureus infection." (PMID 36947494, 2023). "Proinflammatory cytokines are involved in the pathological process of mastitis, mainly including TNF-α, IL-1β, and IL-6, which are associated with the NF-κB pathway that regulates the production of cytokines and is involved in mastitis pathogenesis." (PMID 37948460, 2023). "The TNF plays a key role in the synchronization of the immune response of the mammary parenchyma of cow against mastitis-causing bacteria." (PMID 35812870, 2022). "With regard to TNF-α and its association with bovine mastitis, there are partly inconsistent reports." (PMID 29988549, 2018). "The inflammatory cytokine response of lactating mice infected with large doses of strong versus weak biofilm-forming S. aureus to induce acute mastitis, suggested potential association of mammary tissue damage with high levels of TNF-α." (PMID 28129375, 2017). "Several studies have shown a dysregulated population of milk and serum neutrophils, along with greater concentrations of TNF-α and reactive oxygen species, during the peri-partum period when animals are highly susceptible to severe mastitis." (PMID 28545453, 2017). "In clinical mastitis caused by S. aureus, IL-1β and TNF-α are expressed in the early stages of the infection period, soon followed by a considerable decrease." (PMID 24498088, 2014). "In particular, allele T of TNF-α was associated with a lower number of mastitis cases in lower parities and a higher number of mastitis cases in higher parities." (PMID 23758855, 2013). "Moreover, as one of the most typical messengers in the inflammation family, the expression levels of IL-1β, IL-6, and TNF-α can be used to better evaluate the damage caused by mastitis." (PMID 40438409, 2025). "In addition, high levels of IL1, IL8, and TNF-α have shown a strong correlation with the most severe clinical symptoms associated with coliform or endotoxin-induced mastitis." (PMID 39858163, 2025). "During mastitis caused by E. coli, approximately within 10–12 h, the strong inflammatory response began as a consequence of chemotactic neutrophil infiltration, complement components, tumor necrosis factor, and large amount of interleukin are produced." (PMID 35173767, 2021). "Thus, IFN and TNF-α may both contribute to the inflammatory responses associated with mastitis, whether initiated by infection or milk stasis." (PMID 40564173, 2025). "In addition, cows with subclinical mastitis caused by CNS produce a local immune response in the mammary gland, similar to a variety of inflammatory immune factors including TNF-α and IL-6 produced by Th1 and Th2-mediated immune responses in the presence of exogenous infection." (PMID 31860659, 2019).
mastitis (continued). "The high level of IL-1 and TNF-α in the serum, could induce the activation and migration of neutrophils, and cause apoptosis of endothelial cells and mammary epithelial cells, in bovine and human suffering from acute clinical mastitis." (PMID 30832302, 2019). "Previous studies have indicated that TNF, IL–6, and IL–1β, as pro–inflammatory factors, are highly expressed in cows with mastitis." (PMID 40005889, 2025). "Accordingly, a high relative transcript level of TNF-α has been observed in SCs from buffalo with subclinical mastitis followed by IL-1B, IL-6, and IFN-γ." (PMID 39858163, 2025). "This was accompanied by breast tissue damage and a significant elevation in the levels of the proinflammatory cytokines TNF-α and IL-1β, suggesting the occurrence of mastitis." (PMID 40641870, 2025). "In other experimental studies involving mice and rats, during mastitis-induced episodes, increased levels of IL-1β, IL-6, TNF-α cytokines, and MPO were observed (see Section 4)." (PMID 41148692, 2025). "Among them, TNF is connected to as many as four core targets, indirectly reflecting the high relevance of TNF to the process of mint in treating mastitis in dairy cows." (PMID 40005889, 2025). "When cows are diagnosed with subclinical mastitis prior to parturition, they exhibit higher levels of serum lactate, serum amyloid A, tumor necrosis factor, and lactate." (PMID 40572282, 2025). "TNF-α is also released in high amounts during bovine mastitis and induces an increase in neutrophil ROS production, as already shown in humans." (PMID 40108313, 2025). "IFN-γ and TNF-α, along with other cytokines, have been detected in breast milk from women with clinical and subclinical mastitis." (PMID 40564173, 2025). "In a murine acute mastitis model, levels of TNF-α were increased in mammary glands after a lipopolysaccharide challenge, and transcriptome analysis revealed the upregulation of Nos2 and genes involved in the IFN-γ response and TNF-α signaling." (PMID 40564173, 2025). "Safak and Risvanli (2022) found the TNF‐α concentration to be lower in milk from cows with subclinical mastitis with high somatic cell count (SCC)." (PMID 39792067, 2025). "During mastitis, mammary tissues exhibit elevated levels of inflammatory factors such as TNF-α, IL-6, IL-8, and IL-1β." (PMID 39860009, 2025). "Utilizing the PPI network, the topological parameters of Betweenness unDir, Closeness unDir, and Degree unDir were employed to predict the core targets for mint in treating mastitis in dairy cows, which include TNF, IL–6, STAT–3, IL–1β, FGF–2, IFNG, and ESR–1." (PMID 40005889, 2025). "The results demonstrated that CB significantly alleviated LPS-induced mastitis by downregulating the expression of pro-inflammatory factors IL-1β, TNF-α, and the NLRP3 inflammasome while also reducing cell apoptosis." (PMID 40243637, 2025). "It has been reported that breast milk from women with subclinical mastitis exhibits a predominant Th1/proinflammatory cytokine profile, including TNF-α, IL-6, IL-8, IL-17, RANTES, IL-12p40/70, IFN-α, IFN-γ, CXCL-9, IP-10, MIP-1α, and MIP-1β." (PMID 40564173, 2025). "Immunohistochemically, the localization of TNF‐α within the architecture of udder in cow clinically infected with mastitis was clearly seen in response to inflammatory status of the tissue." (PMID 41026010, 2025). "In conditions such as mastitis, the release of pro-inflammatory cytokines, including TNF-α, IL-1β, IL-6, and IL-8, significantly intensifies the inflammatory response, thereby exacerbating tissue damage and pathological alterations." (PMID 40666730, 2025). "Network pharmacology and molecular-docking analyses revealed that quercetin, lignans and kaempferol were the main active components of Gongying San in the treatment of mastitis, and TNF, IL-6, IL1β, ICAM1, and CXCL8 were its key targets." (PMID 40552082, 2025).